CBFB (core-binding factor subunit beta)
Diseases named in the same sentence as CBFB in open-access papers (continued):
Sharing a sentence is not in itself a finding about the gene and the disease.
chronic lymphocytic leukemia (6 papers, 2019 to 2022). "In addition, Circ-CBFB has been exhibited to be overly expressed in chronic lymphocytic leukemia (CLL) and serves as a diagnostic and prognostic biomarker for CLL." (PMID 31601173, 2019). "For instance, circ-CBFB contributed to the proliferation ability while suppressed the apoptosis of chronic lymphocytic leukemia cells through targeting miR-607/FZD3/Wnt/beta-catenin signaling." (PMID 32782441, 2020). "The corresponding AUC value for circ-CBFB was 0.80 in chronic lymphocytic leukemia." (PMID 35513849, 2022). "Similarly, circ-CBFB was found to be highly expressed in chronic lymphocytic leukemia cells; its knockdown significantly inhibited the proliferation of these cells, prevented cell cycle progression, and induced apoptosis." (PMID 31781492, 2019). "In chronic lymphocytic leukemia (CLL) cells, circ-CBFB indirectly upregulates Fzd3 expression and downstream Wnt/β-catenin signaling by inhibiting miR-607." (PMID 34671643, 2021). "Further studies revealed that circ-CBFB acts as a sponge for miR-607 to reduce its levels, promote expression of the FZD3 target gene, and promote the activation of the Wnt/β-catenin pathway and subsequent progression of chronic lymphocytic leukemia." (PMID 31781492, 2019).
myeloid neoplasm (5 papers, 2015 to 2025). Proliferation of myeloid cells originating from a primitive stem cell. "The downregulation of TRADD expression (16q22) and deletion of CBFB (16q22.1) in patients with myeloid neoplasms have been associated with poor prognosis." (PMID 40282453, 2025).
osteosarcoma (5 papers, 2010 to 2025). A usually aggressive malignant bone-forming mesenchymal neoplasm, predominantly affecting adolescents and young adults. "High expression of CBFβ was shown to be associated with poor outcome in osteosarcoma patients." (PMID 31610798, 2019). "Importantly, we have found a new molecular mechanism that promotes osteosarcoma cell growth and provided preclinical evidence for the CDK11p110-mediated CBFβ pathway as a molecular marker to predict osteosarcoma metastasis risk." (PMID 31610798, 2019). "High expression of CBFβ is associated with poor outcome in osteosarcoma patients." (PMID 31610798, 2019). "CDK11p110 expression is ubiquitous and constant throughout the cell cycle, and CBFβ is maintained at high levels during the cell cycle in osteosarcoma cells." (PMID 31610798, 2019). "Our results demonstrated that CDK11p110 induced CBFβ promoter activity in a dose-dependent manner in two osteosarcoma cell lines." (PMID 31610798, 2019). "Four out of eight osteosarcoma tissue samples showed that both CBFβ and CDK11 proteins were highly expressed." (PMID 31610798, 2019). "In accordance with previous studies, we demonstrated that CBFβ is highly expressed in osteosarcoma cell lines, and especially highly expressed in osteosarcoma metastasis cell lines." (PMID 31610798, 2019). "Clinical relevance and function of core-binding factor subunit beta (CBFβ) were further accessed in osteosarcoma." (PMID 31610798, 2019). "We utilized global gene expression profiles after CDK11 knockdown by siRNA and discovered that CDK11 increases CBFβ -dependent transcriptional activation in osteosarcoma cells." (PMID 31610798, 2019). "We identified CDK11p110, but not CDK11p58, in the transcriptional regulation of core-binding factor subunit beta (CBFβ) expression in osteosarcoma cells, which is important for bone cell development and formation of the skeleton." (PMID 31610798, 2019). "We subsequently demonstrated that CBFβ depletion reduces cell viability, and migration and invasion activities of metastatic osteosarcoma cells." (PMID 31610798, 2019). "Our data suggest that a direct link exists between the CDK11p110- CBFβ pathway and osteosarcoma cell growth and migration." (PMID 31610798, 2019). "Consistently, Matrigel invasion assays identified that the average numbers of osteosarcoma cells that were invading through the Matrigel after treatment with CBFβ siRNA were significantly lower than the blank control and the non-specific siRNA groups." (PMID 31610798, 2019). "Taken together, these results demonstrate that CBFβ plays a role in promoting osteosarcoma cell growth and invasion, similar to the roles of CDK11 in cancers." (PMID 31610798, 2019). "Notably, expression levels of CDK11 and CBFβ protein are both extremely low in normal bone osteoblast cells, but are significantly higher in osteosarcoma cell lines." (PMID 31610798, 2019). "Expression of CBFβ contributes to the proliferation and metastatic behavior of osteosarcoma cells." (PMID 31610798, 2019). "Although CBFβ has been reported to play important roles during skeletal development in previous studies, the role of CBFβ in osteosarcoma are remains unknown." (PMID 31610798, 2019). "Furthermore, CDK11p110 induced CBFβ promoter activity in a dose-dependent manner in both of the osteosarcoma cell lines." (PMID 31610798, 2019). "Similarly, higher expression of CBFβ in osteosarcoma patients also predicted a significantly reduced survival rate (P = 0.0050)." (PMID 31610798, 2019). "CBFβ was also observed in the osteosarcoma cell line, UMR-106, and HeLa cells." (PMID 20591170, 2010). "Therefore, we further investigated the functional role of CBFβ in osteosarcoma." (PMID 31610798, 2019).
osteosarcoma (continued). "In the current study, we have established that CBFβ is a CDK11 transcriptional target and promotes osteosarcoma cell growth and metastasis." (PMID 31610798, 2019). "High CBFβ expression correlated with CDK11 expression and contributed to reduced overall survival in osteosarcoma patients." (PMID 31610798, 2019). "This is the first report demonstrating a transcriptional regulation of CBFβ by CDK11 and that CBFβ can be a potential therapeutic target for osteosarcoma treatment." (PMID 31610798, 2019). "Consistent with this, CBFβ expression is not cell cycle-regulated and is maintained at high levels during the cell cycle in osteosarcoma cells." (PMID 31610798, 2019). "In addition to demonstrating that CBFβ is a transcriptional target of CDK11, CBFβ showed similar biological functions to CDK11 in osteosarcoma." (PMID 31610798, 2019). "We identified a transcriptional role of protein-DNA interaction for CDK11p110, but not CDK11p58, in the regulation of CBFβ expression in osteosarcoma cells." (PMID 31610798, 2019). "We further examined whether the levels of CDK11 correlated with the level of CBFβ in tumor cells by using a high-density tissue microarray (TMA), which included tissues from 73 available characteristics information of osteosarcoma specimens." (PMID 31610798, 2019). "Although no genetic defects have been reported for CBFβ in other types of human cancers, such as in osteosarcoma, there is a report of multiple CBFβ gene copies detected by FISH in a single case of granulocytic sarcoma associated with myeloid leukemia." (PMID 31610798, 2019). "Consistent with this, the protein expressions of CBFβ were also higher in the MNNH/HOS and 143B cell lines than the non-metastatic osteosarcoma U-2OS and KHOS cell lines." (PMID 31610798, 2019).
breast tumors (4 papers, 2019 to 2023). "First, breast tumor-derived mutations of CBFB are loss of function." (PMID 31061501, 2019). "We found that most breast tumors had much lower expression of TAp73, CBFB, and RUNX1 compared to adjacent normal breast tissues." (PMID 33945523, 2021). "Nonetheless, CBFB has a tumor suppressive function in breast tumor and possible in other types of tumors, such as ovarian and prostate tumors." (PMID 31061501, 2019). "Our data show that both the cytoplasmic and nuclear functions of CBFB are important for its breast tumor suppressive function." (PMID 31061501, 2019). "Emerging evidence suggests that CBFB is a tumor suppressor in breast tumors." (PMID 33945523, 2021). "Since dysregulations of translation and transcription are hallmarks of tumorigenesis, breast tumor cells may overcome the barriers of translation and transcription surveillance simultaneously by CBFB downregulation." (PMID 31061501, 2019). "After establishing the cytoplasmic role of CBFB in translation regulation and breast tumor suppression, we aim to assess whether its nuclear function in transcription regulation is also involved in the tumor suppressive function." (PMID 31061501, 2019). "HER2-low breast tumors also had significantly higher mutations rates in CBFB (p < 0.05), PIK3CA (p < 0.05), mitogen-activated protein kinase kinase kinase 1 (MAP3K1; p < 0.05), and AT-rich interaction domain 1A (ARID1A; p < 0.05) as compared with HER2-zero breast tumors." (PMID 35484593, 2022). "HER2-low breast tumors had significantly more frequent mutations in phosphatase and tensin homolog (PTEN; p < 0.001), GATA binding protein 3 (GATA3; p < 0.001), core-binding factor subunit beta (CBFB; p < 0.001), and AKT serine/threonine kinase 1 (AKT1; p < 0.001) than HER2-positive breast tumors." (PMID 35484593, 2022). "Therefore, the frequency of CBFB downregulation in breast tumor may be under-estimated by genome sequencing studies." (PMID 31061501, 2019).
ovarian carcinoma (4 papers, 2017 to 2019). A malignant neoplasm originating from the surface ovarian epithelium. "The results above, coupled with the correlation of high CBFβ levels with metastatic behavior in breast, prostate, and ovarian cancer cells, support the notion that high CBFβ expression in the primary tumor may contribute to metastatic behavior." (PMID 31610798, 2019). "Moreover, CBFβ is essential for invasion and xenograft tumor growth in some solid tumors, including in breast, prostate, and ovarian cancers." (PMID 31610798, 2019). "Of note, CBFB has previously been found to influence BMP signaling in chondrocytes and it has also been shown to have invasive properties in breast, prostate and ovarian cancer cells." (PMID 28077088, 2017).
triple-negative breast carcinoma (4 papers, 2013 to 2025). An invasive breast carcinoma which is negative for expression of estrogen receptor (ER), progesterone receptor (PR), and human epidermal growth factor receptor 2 (HER2). "In contrast, we and others have previously shown that expression of RUNX2 and CBFβ contribute to the metastatic phenotype of triple-negative breast cancer cells." (PMID 32005976, 2020). "We demonstrate that CBFβ is essential to maintain the mesenchymal phenotype of triple-negative breast cancer cells and that CBFβ-depleted cells undergo a mesenchymal to epithelial transition (MET) and re-organise into acini-like structures, reminiscent of those formed by epithelial breast cells." (PMID 32005976, 2020). "Thus, targeting the RUNX/CBFβ complex in this way might be a viable option to treat a sub-group of triple-negative breast cancer patients." (PMID 32005976, 2020).
Acute myelomonocytic leukemia (3 papers, 2017 to 2024). "Fourteen (26%) cases of pDC-AML showed monocytic differentiation including 4 AML with CBFB rearrangement and 10 acute myelomonocytic leukemia." (PMID 35884435, 2022).
osteoporosis (3 papers, 2021). A condition of reduced bone mass, with decreased cortical thickness and a decrease in the number and size of the trabeculae of cancellous bone (but normal chemical composition), resulting in increased fracture incidence. "In summary, this study shows that circ_0062582 affects osteoporosis by regulating CBFB/miR-145, providing the first line of evidence to clarify the underlying regulatory mechanisms of circ_0062582 in the development of osteoporosis in vitro." (PMID 34027799, 2021). "In summary, these results demonstrated that the role of circ_0062582 in osteoporosis is mediated through regulating the expression level of CBFB via miR-145." (PMID 34027799, 2021). "However, no research has shown the role and potential mechanisms of circ_0062582, miR-145 and CBFB in osteoporosis." (PMID 34027799, 2021). "Radiographic and uCT analyses demonstrated that AAV-mediated overexpression of Runx1 with or without its binding partner, Cbfβ, significantly increased bone volume after estrogen depletion induced osteoporosis." (PMID 33476325, 2021).
squamous cell carcinoma (3 papers, 2016 to 2022). A carcinoma arising from squamous epithelial cells. "They found novel somatic mutations in the MAPK1 gene (8%), HLA-B gene (9%), EP300 (16%), FBXW7 (15%), NFE2L2 (4%), and ERBB2 (6%) of 79 squamous carcinomas, and ELF3 (13%) and CBFB (8%) mutations in 24 adenocarcinomas." (PMID 26701206, 2016).
acute myocardial infarction (2 papers, 2022 to 2023). Necrosis of the myocardium, as a result of interruption of the blood supply to the area. "Circ-CBFB/miR-495-3p/VDAC1 is an innovative axis in H/R challenge cardiomyocyte injury, providing new ideas for the management of acute myocardial infarction." (PMID 36835653, 2023).
asthma (2 papers, 2014 to 2019). "To investigate the impact of increased exhausted-like ILC2s resulting from Cbfβ deficiency on inflammation, we created a subacute asthma model with a high dose of papain using congenic mice adoptively transferred with bone marrow cells from either Cbfb+/f PLZF-Cre or Cbfbf/f PLZF-Cre mice." (PMID 30683858, 2019). "By searching PubMed, NFKB1, STAT6, E2F1, USF1, and CBFB were the verified asthma-related TFs, while NFKB1 and STAT6 were the newly discovered asthma-related genes in 2013." (PMID 24790987, 2014).
Autoimmunity (2 papers, 2019 to 2026). The occurrence of an immune reaction against the organism's own cells or tissues. "Several genes, such as TREX1, FLI1, EVI5, IL1RAPL1, are known for their role in autoimmunity, with EVI5 being an established MS risk gene, whereas others, such as CBFB, OPCML and KMT2A, are involved in lymphoproliferative disorders (OMIM)." (PMID 30541027, 2019).
chronic myelomonocytic leukemia (2 papers, 2022 to 2026). A myelodysplastic/myeloproliferative neoplasm which is characterized by persistent monocytosis, absence of a Philadelphia chromosome and BCR/ABL fusion gene, fewer than 20 percent blasts in the bone marrow and blood, myelodysplasia, and absence of PDGFRA or PDGFRB rearrangement. "After an extensive workup, he was diagnosed with AML/CMML (chronic myelomonocytic leukemia) with a normal karyotype with DNMT3A, CBFB, and PTPN11 mutations." (PMID 35656122, 2022).
Cleidocranial Dysplasia (2 papers, 2025). "We recently published the CBFB gene alteration associated with a new skeletal disorder resembling cleidocranial dysplasia." (PMID 40130161, 2025). "Recently, five families with cleidocranial dysplasia (CCD) were identified harbouring presumed loss of function variants in CBFB." (PMID 39894570, 2025).
neuroblastoma (2 papers, 2004 to 2018). Neuroblastoma (NB) is the most common solid, extracranial childhood tumor. "The data obtained in our experiments suggested differential expression of genes such as myb, CBFβ and HMG 1, 3 and 4 proteins with high expression restricted to the pre-B cells while Bcl-6 appeared to be over-expressed specifically in neuroblastoma cells." (PMID 15544702, 2004).
renal carcinoma (2 papers, 2021 to 2022). A carcinoma arising from the epithelium of the renal parenchyma or the renal pelvis. "The transcription factor RUNX1 and cofactor CBFB form a complex that promotes EMT in renal carcinoma and is elevated upon EMT in endometrial cancer." (PMID 36551618, 2022). "For instance, ELK4, CBFB, IFI16, PRRX1, AEBP1, and GATA3 expression was associated with an unfavourable outcome in renal cancer revealing the significance of these TFs (pink and blue colours represent unfavourable and favourable prognosis, respectively)." (PMID 35201514, 2021). "On a similar note, a significant association between the expression of ELK4, CBFB, IFI16, PRRX1, AEBP1, and GATA3 with an unfavourable outcome in renal cancer has been identified in previous reports." (PMID 35201514, 2021).
acquired immune deficiency syndrome (1 paper, 2024). "Our findings suggest that competitive Vif-derived peptides targeting the Vif-CBFβ interaction are promising for the development of novel therapeutic strategies for acquired immune deficiency syndrome." (PMID 38675833, 2024).
acute leukemia (1 paper, 2013). A clonal (malignant) hematopoietic disorder with an acute onset, affecting the bone marrow and the peripheral blood. "RUNX1 (AML1) is a member of the RUNT family of transcription factors and together with its cofactor CBFB (core-binding factor, beta subunit) represents the most common mutational target in human acute leukemia." (PMID 23311859, 2013).
acute monocytic leukemia (1 paper, 2024). Acute monoblastic leukemia (AML-M5), is one of the most common subtypes of acute myeloid leukemia (AML) that is either comprised of more than 80% of monoblasts (AML-M5a) or 30-80% monoblasts with (pro)monocytic differentiation (AML-M5b). "P1 was also significantly enriched in WHO subtype AML with KMT2A rearrangement (q < 0.05), acute monocytic leukemia, and AML with CBFB::MYH11 fusion." (PMID 38724673, 2024).
adenoma (1 paper, 2009). A neoplasm arising from the epithelium. "The frequency and intensity of CBFB expression increased significantly (P=0.01, Fisher's exact test) from normal mucosa to adenoma and again from adenoma to adenocarcinoma (P<0.001, Fisher's exact test)." (PMID 19156145, 2009).
Allergy (1 paper, 2019). An allergy is an immune response or reaction to substances that are usually not harmful. "Thus, severe allergy induced hyporesponsive TIGIT+ IL-10+ ILC2s similar to Cbfβ-deficient ILC2s." (PMID 30683858, 2019).
autoimmune disease (1 paper, 2013). A disorder resulting from loss of function or tissue destruction of an organ or multiple organs, arising from humoral or cellular immune responses of the individual to their own tissue constituents. "Treg-specific deletions of IRF4 and Cbfβ resulted in Th2-type inflammatory diseases such as lymphoproliferation, autoimmune disease in the lung and skin, and hyperproduction of IgE." (PMID 24058613, 2013).
B-acute lymphoblastic leukemia (1 paper, 2023). "Recently, NOTCH3, PAX5, CBFB, and particularly ACD were shown to drive the activated RAS pathway and monosomy 7 to B-acute lymphoblastic leukemia." (PMID 36980962, 2023).